STMN1 (stathmin 1)
Diseases named in the same sentence as STMN1 in open-access papers (continued):
Sharing a sentence is not in itself a finding about the gene and the disease.
cancer (continued). "In addition, elevated concentration of stathmin-1 was related to lymphatic metastasis and late staged cancer." (PMID 34527593, 2021). "To figure out whether there is a general correlation between FoxM1 and STMN1 in cancers, we then analyzed the expression patterns of them." (PMID 33526768, 2021). "This led us to hypothesize that FoxM1 may regulate STMN1 at the transcriptional level in cancer cells." (PMID 33526768, 2021). "Since FoxM1 and STMN1 both play important roles in the process of cell cycle regulation, we wondered to know whether there is a functional link in cancers." (PMID 33526768, 2021). "miR-34a downregulated STMN1 to inhibit cancer proliferation and colony formation." (PMID 34860853, 2021). "So that whether the mechanisms of PTEN function is available in all cancer types or whether inhibiting STMN1 is a viable target for all cancer subtypes needs to be further explored." (PMID 34253824, 2021). "The mechanisms of STMN1 function in cancers are also studied." (PMID 34253824, 2021). "The STMN1 protein displays a complex pattern of activity and phosphorylation in cancers." (PMID 31675377, 2019). "Moreover, studies imply that cancer patients with low expression of STMN1 mRNA will have a favorable clinical efficacy after being treated with Taxol regimens." (PMID 28056823, 2017). "Indeed, it has been reported that the MEK-mediated phosphorylation of STMN1 is a key process of cancer cell migration." (PMID 28686225, 2017). "Recently, the possible mechanisms that might elucidate the functions of STMN1 in cancer have attracted increasing attention." (PMID 27349455, 2016). "Therefore, anti-STMN1 therapy in combination to chemotherapeutic drugs has been proposed as a new therapeutic approach to cancer treatment." (PMID 26466335, 2015). "However, on the basis on the relationship of changes in STMN1 gene expression and efficacy of therapies based on the taxane or vinca alkaloids in cell cultures and in cancer patients, it can be concluded about the potential importance of such genetic change." (PMID 26220844, 2015). "STMN1 is a biomarker for gastric and non-small cell lung cancers." (PMID 23555679, 2013). "Stathmin1 (STMN1) is a candidate oncoprotein and prognosis marker in several kinds of cancers." (PMID 22470493, 2012). "STMN1 was mainly localized in breast epithelial, stromal, vascular endothelial and cancer cells." (PMID 23071542, 2012). "In addition to functioning in the hematopoietic system, miR-223 is in close relationship with multiple malignancies, given that miR-223 targets (e.g., IGF-1 receptor and stathmin 1) have been disclosed to impact the hallmarks of cancer, involving proliferation, invasion, metastasis, etc.." (PMID 35515121, 2022). "However, there are few studies investigating the molecular mechanism of STMN1 in cancers." (PMID 35186166, 2022). "The over-expression of Stathmin-1, regarded as microtubule depolymerization protein, is related to the process of tumor spread, adverse clinical outcomes, and chemoresistance in many types of cancer, especially squamous cell carcinoma, by controlling cell division, proliferation, and migration." (PMID 34527593, 2021). "Maybe STMN1 treatment should be avoided in PTEN null cancers." (PMID 34253824, 2021). "Additionally, the expression of Ki-67 reduces in cancer tissues with the depletion of STMN1." (PMID 33526768, 2021). "Therefore, STMN1 has been viewed as a therapeutic target for cancer treatment." (PMID 33922244, 2021). "Thus, STMN1 plays a pivotal role in cell division and proliferation in cancer cells." (PMID 33201835, 2020).
cancer (continued). "A recent study showed that TKIs could enrich cancer stem cells and induce epithelial–mesenchymal transitions, subsequently resulting in drug resistance, and these properties are associated with aberrant activation of the AKT/FOXM1/STMN1 axis." (PMID 30782607, 2019). "Additionally, STMN1 is a possible marker of cancer cell proliferation." (PMID 31653009, 2019). "In fact, the levels of phospho-STMN1 in cancer cells may serve as a biomarker of VB sensitivity." (PMID 30082792, 2018). "Consequently, these phenomena prompted us that STMN1 promoted the progression of human cancers, and it might be a potential therapeutic target for cancer therapy." (PMID 27349455, 2016). "This nanoparticle can improve the microtubule stability by interfering the expression of STMN1, thereby increasing the sensitivity to PTX, blocking cells in the G2/M phase, and ultimately leading to cancer cell death." (PMID 41361792, 2025). "The expression levels of STMN1 and PRDX1 genes are significantly correlated with MSI status in many cancers, and the strength of the correlation varies depending on cancer type." (PMID 41403955, 2025). "Consistent with the microtubule‐targeting activity of VU‐0365114, cancer cells with higher levels of mitotic regulators (CDK1, CCNB1, and STMN1) were more sensitive to VU‐0365114." (PMID 37842807, 2024). "KATNA1, STMN1 and KIF2C are key proteins involved in microtubule dynamics, with implications in cancer progression and potential targets for anticancer drug development." (PMID 39175104, 2024). "Furthermore, co-immunoprecipitation assays revealed an interaction between STMN1 and β3-Tubulin and that inhibition of STMN1 expression could promote the expression of β3-Tubulin, thereby inhibiting cancer cell proliferation and promoting cancer cell apoptosis." (PMID 37165308, 2023). "In most cancers, GPX2, HNF4A, and STMN1 were hypomethylated, while the majority of cancer genes exhibited hypermethylation." (PMID 37304867, 2023). "Twelve components were included in the MAPK signalling pathway, and of these, EFNA3, STMN1, PAK1, and TNF have previously been found to regulate EMT in cancer progression." (PMID 37225681, 2023). "Reduced expression of both reporter proteins and endogenous expressions of stathmin-1 (STMN1) and insulin-like growth factor-1 receptor (IGF-1R) functionally inhibit the proliferation of these cancer cells." (PMID 35832790, 2022). "Our study showed that FoxM1 upregulates STMN1 by transcriptional regulation, and the FoxM1-mediated transcriptional activation of STMN1 can promote cell proliferation and survival both in vitro and in vivo in LIHC, GC and CRC cancers." (PMID 33526768, 2021). "Cluster 4 showed high expression of cell cycle‐related genes for markers such as PCNA, MCM5, MKI67, STMN1, and CDK1, probably owing to the immune response to cancer neo‐epitopes." (PMID 33513276, 2021). "Stathmin 1 (STMN1) is an oncoprotein that destabilizes microtubules and promotes cancer cell migration and invasion." (PMID 33922244, 2021). "The anti-cancer effects of miR-193a-3p are precluded by the repression of multiple target genes, including cancer related genes such as CCND1, KRAS, RASSF1, STMN1, and MCL1." (PMID 33747358, 2021). "Key cancer-related pathways and proteins that these genes can regulate include the AKT/GSK-3β/SNAIL pathway, MMP-9, CD44 and STMN1 which are involved in EMT and metastasis." (PMID 33374923, 2020). "Depletion of two SAM downregulated genes STMN1 and TAF15 reduces cellular transformation and invasiveness, providing evidence that SAM targets are genes important for cancer growth and invasiveness." (PMID 29340097, 2017). "The KEGG pathway analysis results indicated that among 26 genes some of them were found to have roles in cancer related pathways like cell cycle (MCM2), Jak-STAT (SOCS1), MAPK (STMN1), PPAR signaling pathways (ME1)." (PMID 25978727, 2015).
cancer (continued). "Notably, STMN1+ cECs and MYF5+ MSCs were found to be spatially closer to cancer cells than to other cell types, particularly in Pt27 and Pt59, who exhibited progressive disease." (PMID 40107247, 2025). "Since the co-regulation of STMN1 with HGF and MET protein expression is indicative of a coordinated mechanism, the differential phosphorylation of STMN1 was evaluated to determine its impact on cancer progression and metastasis." (PMID 40723207, 2025). "Notably, we also found a cluster of cells that exhibited higher expression of a set of cell cycle-related genes (CENPF, NUSAP1, PTTG1, STMN1, TOP2A, and TUBA1B), which was consistent with proliferative CAFs (pCAFs) in a previous pan-cancer study of CAFs." (PMID 37833788, 2023). "Furthermore, PTEN loss enhanced STMN1 upregulation and ameliorated STMN-mediated cancer migration and invasion, indicating that PTEN is an upstream regulator of STMN1." (PMID 36188577, 2022). "STMN1 knockdown upregulated MMP1 and MMP9, responsible for cancer invasion." (PMID 36188577, 2022). "Previous studies have clarified that miR‐101‐3p regulates various pivotal oncogenes and that downregulation of this miRNA affects cancer cell proliferation, metastasis, drug resistance, and angiogenesis via targeting of several oncogenic targets, e.g. EZH2, STMN1, VHL, SOX2, and DNMT3A." (PMID 31755218, 2020). "Importantly, STMN1 is inversely correlated to stress fiber formation, whereas PKM2 is a key glycolytic enzyme which can impact cancer cell migration, matrix metalloproteinase expression, and FAK/integrin activation." (PMID 31959624, 2020). "Our work demonstrates that STMN1 phospho-levels can enhanced the efficacy of an anti-cancer molecule that was not, until now, considered to be practical for GBM37." (PMID 30082792, 2018). "The modules also contained genes like LRRN4CL, NAV3 and STMN1 that have not yet been investigated in cancer research." (PMID 29371966, 2017). "Tissue microarray statistical results showed that the expressions of BRCA1 and MAPTin cancer tissues were significantly lower (p<0.01) than that in adjacent tissues, whereas the expressions of STMN1 and TUBB3 in cancer tissues were significantly higher (p<0.01) than that in adjacent tissues." (PMID 29113350, 2017). "In contrast to cancer-derived cell lines, STMN1 depletion is not deleterious to nontransformed cells; in fact, STMN1 knockout mice are viable." (PMID 25897432, 2015). "Previous studies had shown the evidence of ANKHD1 in the malignant phenotype of cancer cells, including promoting cancer cell proliferation, migration, invasion, and tumorigenesis, by positively regulating of YAP1, JAK/STAT, and STMN1, and negatively regulating p21." (PMID 34743406, 2022). "In addition, this is the first study showing the effects of this binding domain on genes involved in cancer, such as STMN1 or SSBP1, which are not direct targets of RUNX2." (PMID 30463392, 2018). "Notably, hispidin could induce larger fluctuations in microtubule regulatory proteins, such as STMN1 phosphorylation at Ser16, in SGC-7901 cells than in GES-1 cells because cancer cells usually exhibit higher expression levels or activity of these kinases." (PMID 28460485, 2017). "Thus, the mechanisms by which the interplay between the four STMN1 phosphoserines regulate cell cycle progression, proliferation, and metastasis, and whether or not these activities are cancer cell type specific, remain to be established." (PMID 40723207, 2025). "Not surprisingly, similarity among different cancer types was identified in only 6 out of 23 clusters, including E3 (IRS2, KRT6A), E5 (CD24, STMN1), E8 (GKN1, MUC5AC), E9 (PHGR1, TFF3), E10 (TFF3, TPO) and E13 (VTN and ITIH5)." (PMID 36333338, 2022). "Stmn1 was up-regulated in the TCDD, PCB153 and human HCA expression profiles suggesting that while it is a good marker for different types of human cancer, it may not be a valid biomarker for DLC exposure in Sprague Dawley rats." (PMID 20959002, 2010).
cancer (continued). "However, in men, inhibition of STMN1 and LRRFIP2 could not overcome dysregulation of the MAPK and Wnt signaling pathways or aberrant cell cycle and apoptosis regulation, thus resulting in cancer." (PMID 26895224, 2016).
infection (10 papers, 2020 to 2025). The state of being infected such as from the introduction of a foreign agent such as serum, vaccine, antigenic substance or organism. "To explore the function of CTTN, SERBP1, and STMN1 in infection of NiV, we conducted pseudoviral infection experiments." (PMID 38612921, 2024). "Analysis of the expression profiles in our study revealed that miR-449a and miR-449b were highly expressed at the early stage of infection, whereas the expression of their target genes L1CAM, MYO3B, SCIN, and STMN1 decreased." (PMID 38178220, 2024). "We suspect that the reason why SERBP1 and STMN1 do not significantly affect NiVpv infection is due to the limitation that the pseudovirus we used can only carry out one round of infection and cannot replicate." (PMID 38612921, 2024).
adenocarcinoma (6 papers, 2017 to 2025). A common cancer characterized by the presence of malignant glandular cells. "Finally, dual immunofluorescence (IF) staining confirmed co-expression of STMN1 and Ki67 in both benign and adenocarcinoma prostate tissues, further supporting the association of STMN1 expression with a proliferative phenotype." (PMID 39776361, 2025). "Additionally, dual IF staining revealed the co-expression of STMN1 with Ki67 in luminal cells in both benign and adenocarcinoma prostatic tissues, reinforcing the association of STMN1 expression with a proliferative phenotype." (PMID 39711570, 2024). "These Stmn1-positive cells, which lack the expression of T-antigen, proliferation markers, and NE markers, may represent a transitional population moving from adenocarcinoma to NEPC, a process previously observed during PCa progression." (PMID 39776361, 2025). "Additionally, significant predictors for DFS in patients with an adenocarcinoma component were STMN1 and GRP78/BiP levels, and significant predictors for DFS in patients with a non-adenocarcinoma component were disease stage and VEGFR2 level." (PMID 31653009, 2019). "Additionally, significant prognostic markers for DFS in patients with an adenocarcinoma component were STMN1 and GRP78/BiP levels and disease stage and VEGFR2 level in patients with a non-adenocarcinoma component." (PMID 31653009, 2019). "In summary, studies of human samples revealed a correlation between low STMN1 expression and more frequent CIC structure formation, which is compatible with our in vitro findings, and this condition is associated with poorly differentiated adenocarcinoma and worse patient survival." (PMID 40225568, 2025). "The transgenic adenocarcinoma of the mouse prostate (TRAMP) model, which mimics the development of human NEPC, was used to investigate the correlation between STMN1 expression and NEPC development." (PMID 39711570, 2024). "Univariate analysis identified disease stage and STMN1 and TS levels as significant prognostic markers for OS in patients with an adenocarcinoma component, and disease stage and VEGFR2 and TUBB3 levels as significant prognostic markers for OS in patients with a non-adenocarcinoma component." (PMID 31653009, 2019).
hematological malignancies (2 papers, 2015 to 2023). "B/My MPAL blasts depicted significant overexpression genes such as STMN1 and SOX4, which have been previously associated with other hematological malignancies, such as AML and ALL." (PMID 37845689, 2023).
neurodegenerative disease (2 papers, 2022 to 2025). A disorder of the central nervous system characterized by gradual and progressive loss of neural tissue and neurologic function. "Stathmin 1 (STMN1) as a cytosolic phosphoprotein that regulated microtubules dynamics, impaired axonal transport, and cause human neurodegenerative diseases." (PMID 36440278, 2022).
blood cancer (1 paper, 2025). "On the other hand, patients with blood cancer who have low cell proliferation rates, such as multiple myeloma, have STMN1 levels similar to healthy donors." (PMID 40982350, 2025). "The prognostic role of STMN1 in hematological neoplasms remains a topic of debate." (PMID 40982350, 2025).
hematological cancers (1 paper, 2025). "Given the substantial body of evidence supporting the involvement of STMN1 in oncogenesis, not only in hematological cancers but also in various solid tumors, selective STMN1 inhibitors have yet to be developed and could pave the way for significant advances in antineoplastic therapy." (PMID 40982350, 2025).
psychiatric disorder (1 paper, 2023). A disorder characterized by behavioral and/or psychological abnormalities, often accompanied by physical symptoms. "Genes in the Stathmin-1 signaling pathway have additionally been implicated in psychiatric disorders 96–99 comorbid with suicidality." (PMID 37398042, 2023).
STMN1 also shares sentences with these, for which no sentence is quoted: lymphoma (4 papers); atherosclerosis (2); colon cancer (2); COVID-19 (2); depression (2); metastatic disease (2); pancreatic ductal adenocarcinoma (2); skin carcinoma (2); abortion (1); acute promyelocytic leukemia (1); amyotrophic lateral sclerosis (1); attention deficit-hyperactivity disorder (1); autism (1); Autoimmunity (1); Azoospermia (1); bipolar disorder (1); Burkitt lymphoma (1); cholangiocarcinoma (1); clear cell carcinoma (1); colorectal tumor (1); cutaneous squamous cell carcinoma (1); diffuse large B-cell lymphoma (1); dyslexia (1); esophageal granular cell tumor (1); fibrosarcoma (1); fibrosis (1); follicular lymphoma (1); ganglioneuroblastoma (1); ganglioneuroma (1); head and neck squamous cell carcinoma (1).
A further 28 diseases each share a sentence with STMN1 in 1 paper.